PAK1 (p21 (RAC1) activated kinase 1)
Diseases named in the same sentence as PAK1 in open-access papers (continued):
Sharing a sentence is not in itself a finding about the gene and the disease.
tumor (continued). "In addition, we have also meticulously designed and synthesized a multitude of potent PAK1 inhibitors in the early stages, which have exhibited remarkable potential in the treatment of TNBC through their adept regulation of energy metabolism and the tumor microenvironment." (PMID 40302782, 2025). "In addition, p21-activated kinase 1 (PAK1), an oncogene involved in activation of MAP kinase and MET signaling, was identified as a potential target of miR-494, with an inverse correlation with the miRNA and partial reversal of the tumor-inhibitory effects seen when PAK1 was re-expressed." (PMID 34356891, 2021). "Taken together, these results demonstrate that PAK1 regulates chemotactic extravasation by dissolving invadopodia in the absence of external cues, and this may facilitate tumor cell extravasation and metastatic colony formation in chemotactic rich areas supportive of growth." (PMID 30651600, 2019). "PAK1 and PAK4 are activated differently, however little is known about the unique signalling pathways or the substrates of these two family members and how these differences may impact on the effect that these proteins have on the invasive potential of tumours." (PMID 27765920, 2016). "While not extensively utilized in tumor research, IPA-3, serving as a direct non-ATP competitive PAK1 inhibitor, has garnered acclaim in studies pertaining to cellular immune-inflammatory diseases and PAK1-mediated cardiac cell development." (PMID 40332759, 2025). "Here, we used an immunocompromised SCID model to dissect immune-independent isoform-specific effects of PAK1 vs. PAK4 on tumour vasculature and gemcitabine response—focusing on tumour and vascular mechanisms without the interference of immune system effects." (PMID 41228228, 2025). "P21-activated kinase 1 (PAK1) and PAK4 play key roles in tumorigenesis, but their specific effects on tumour blood vessels and treatment response are not well understood." (PMID 41228228, 2025). "The double knockout of PAK1 and PAK4 did not inhibit tumour growth, although it stimulated vascular normalisation, indicating an outcome balanced between PAK1 and PAK4." (PMID 41228228, 2025). "This study, however, was an effect of PAK1 and PAK6 gene knockout in PCa cells on tumor angiogenesis, and not an effect of direct suppression of PAKs in endothelial cells." (PMID 37190165, 2023). "However, the treatment of cannabis oil could not further reduce the tumour growth in PAK1 KO mice." (PMID 33126623, 2020). "Upregulation of the anti-apoptotic genes BCL2L2, BAG3, and downregulation of pro-apoptotic genes DAXX, FAF1, PAK1, DFFA, ENDOG was found in reprogrammed tumours pointing to a cell cycle arrest without engagement of the apoptotic pathway." (PMID 29662623, 2018). "The observation that PAK1 knockout did not have a significant effect on the number of tumours or tumour incidence in the colon and rectum of 10-week old APC∆14/+ mice is perhaps due to the lower numbers and slower development of tumours in the colon and rectum of these mice." (PMID 28629331, 2017).
infection (35 papers, 2010 to 2025). The state of being infected such as from the introduction of a foreign agent such as serum, vaccine, antigenic substance or organism. "Thus one must exercise caution when attempting to extrapolate what is known about the role of PAK1 from one type of pathogenic infection to another." (PMID 28430160, 2017). "Upon infection with H. pylori, cortactin not only undergoes CagA-mediated tyrosine dephosphorylation but also serine phosphorylation at S-405 and S-418 by PAK1 or ERK1/2 serine-threonine kinases." (PMID 31936446, 2020). "Bartonella bacilliformis-stimulated PAK1 activation occurs by 1 h after infection of human endothelial cells." (PMID 28430160, 2017). "Pronounced activation of PAK1 by H. pylori (strains P1 and P12) upon infection of the gastric adenocarcinoma cell line AGS occurs 45 min after infection." (PMID 28430160, 2017). "The signals transmitted by PAK1 regulate a wide variety of processes during all stages of an infection or a pathogen’s life cycle in its human host." (PMID 28430160, 2017). "EV1 infection is prevented by inhibitors of macropinocytosis, and the use of dominant-negative or highly kinase active PAK1 constructs demonstrated the PAK1 dependence of EV1 entry via the α2β1 integrin receptors." (PMID 28430160, 2017). "In this review we discuss the latest insights into the surprisingly central role human PAK1 plays for the infection by such different infectious disease agents as viruses, bacteria, and parasitic protists." (PMID 28430160, 2017). "PAK1 subsequently becomes inactivated at 2 h and 4 h post-infection, and is then activated again by 12 h post-infection." (PMID 28430160, 2017). "Knock-down experiments using specific siRNAs indictated that Rho GTPase Rac1 regulates EV1 infection and is possibly the upstream regulator of PAK1." (PMID 28430160, 2017). "PAK1 was shown to activate human MEK1 in erythrocytes upon infection with Plasmodium falciparum (3D7) and P. berghei." (PMID 28430160, 2017). "Both PAK1 and 2 have roles in various host-driven responses to pathogen infection, including anti-pathogen signalling and immune regulation." (PMID 28430160, 2017). "This review therefore also includes several examples of extracellular bacterial pathogens that affect PAK1 signalling in human cells during the course of infection." (PMID 28430160, 2017). "PAK1 also orchestrates the enhanced actin-dependent migratory responses in the host cell that are triggered upon infection by bacterial pathogens." (PMID 28430160, 2017). "After specific inhibition on actin, Na+/H+ exchanger, receptor tyrosine kinase, Rac1, Pak1, myosin II, and protein kinase C, the entry and infection of FMDV significantly decreased." (PMID 26757826, 2016). "Consistent with cellular protection, the PAK1-CA expression significantly recovered behavioral defects from 2 weeks after the infusion and infection, compared to those in the GFP-expressing control group." (PMID 27121078, 2016). "Pak1 RNAi infection of Rb-/- MC3T3 cells increased the intensity of beta-catenin labeling in intercellular spaces, suggesting a partial restoration of adherens junctions (arrow), compared to Rb-/- MC3T3 cells infected with scrambled control adenovirus." (PMID 26555075, 2015). "Infection of Rb-/- MC3T3 cells with Pak1 Adeno-RNAi dramatically decreased Pak1 expression relative to an Adeno-scrambled control, as assessed by Pak1 immunoblot." (PMID 26555075, 2015). "Inhibition of PAK1 using lentiviral PAK1-shRNA infection or treatment using the group I PAK inhibitor FRAX597 in Ben-Men-1 cells showed attenuation of pS6." (PMID 26219339, 2015). "Both infection and endocytic uptake were reduced when some of Cdc42's downstream effectors were inhibited including PAK1 (IPA-3), N-Wasp (wiskostatin), and moderately when Arp2/3 (CK-869) was targeted." (PMID 23593008, 2013). "At different times post infection, samples were collected and analyzed by immunoblotting using an anti-phospho-Pak1 Thr423 antibody." (PMID 22719252, 2012).
infection (continued). "The infection of gfpZEBOV was reduced >95% in cells expressing the DN Pak1 protein than in cells expressing the wild-type Pak1 protein." (PMID 20862315, 2010). "First, we measured the effect of siRNA-mediated suppression of endogenous Pak1 and found that the infection of gfpZEBOV was significantly reduced in cells transfected with Pak1 siRNA." (PMID 20862315, 2010). "Additionally, RABV induces biphasic dynamics of epidermal growth factor receptor (EGFR)-phosphatidylinositide-3 kinase (PI3K)-Rac1 signaling at early infection and impedes Rac1-p21-activated kinase 1 (Pak1) transduction later." (PMID 38809020, 2024). "Although both we and Wu showed that PAK1 was activated in response to SARS-CoV-2 infection, PAK1 activation occurred 2 h post-infection in Caco-2 cells in our study, while PAK1 activation occurred 36 h post-infection in the human nasal epithelial cells in Wu’s study." (PMID 37806990, 2023). "Notably, this is the first work to examine the effects of PAK1 on the regulation of adaptive immune response during pathogen infection." (PMID 33124146, 2020). "Moreover, numerous Ser/Thr kinases (STKs) were either increased (e.g., GRK2, ROCK2, ROCK1, PAK1) or decreased (e.g., BMP2K, TNIK, MYLK, and NRBP1) in expression in the patient samples, suggesting a widespread change in the kinome caused by pathogen infection." (PMID 38389037, 2024). "However, the way in which PAK1 mediates its adaptive cellular effects during pathogen infections remains unclear." (PMID 33124146, 2020). "PAK1 and PAK2 affect infection progression (virus, bacteria, and parasitic protists) at various stages, promoting pathogens entry into, replication within, survival, and secretion from host cells." (PMID 33796531, 2021). "The activation of serine/threonine kinases PAK1 and ERK1/2, combined with the inactivation of c-Src, strictly correlates with the elongation phenotype that H. pylori induces between 4 and 8 h of infection." (PMID 31936446, 2020). "The role of both cellular factors during ASFV infection was also demonstrated by transfecting cells with dominant-negatives for both Pak-1 (pEGFP-Pak-1-AID) and Rac-1 (pcDNA-Rac-1 N17), which inhibited the infection and the synthesis of ASFV early proteins." (PMID 29117102, 2017). "During infection these viruses express a kinase, US3, which phosphorylates and activates PAK1 (p21-activated kinase Group I) to mediate changes in the actin cytoskeleton." (PMID 27977778, 2016). "To further investigate the effect of Pak1 activation on FMDV uptake, we treated BHK-21 cells with IPA-3 30 min before FMDV infection, and IPA-3 was maintained during the whole infection period." (PMID 26757826, 2016). "Rac1-GTP was found together with the pulled Pak1-PBD-Agarose Beads after 10 min post ASFV infection, slightly diminishing 30 min after the infection." (PMID 22719252, 2012). "We found that suppression of both Pak1 and CtBP/BARS activity by siRNA or expression of a DN form of Pak1 reduced virus entry and infection." (PMID 20862315, 2010). "Inhibition of key regulators of macropinocytosis including Pak1 and CtBP/BARS as well as treatment with the drug EIPA, which affects macropinosome formation, resulted in significant reduction in ZEBOV entry and infection." (PMID 20862315, 2010). "In the case of JEV infection, it has been shown that entry is independent of clathrin, while the regulatory proteins of actin filaments, such as RHOA, RAC1, proteins of the ARP2/3 complex, and the N-WASP family (LIMK1, PAK1, and ROCK2), are crucial for the establishment of infection." (PMID 40733526, 2025). "Further investigations found several factors, such as the epidermal growth factor receptor (EGFR), phosphoinositide 3-kinase (PI3Ks), p21-activated kinase-1 (PAK1), Niemann-Pick C1 (NPC1), and NPC2, as potential factors in ASFV entry, highlighting the complexity of ASFV infection mechanisms." (PMID 39943192, 2025).
infection (continued). "When ΔPAK1 Hap1 cells were transfected with Emerald-tagged PAK1 (Em-PAK1) prior to infection, Em-PAK1 was enriched at WT, but not ΔSopE1/E2, Salmonella entry foci." (PMID 34460869, 2021). "Upon infection of human brain microvascular endothelial cells (HBMEC), cells that form the blood-brain barrier, E. coli K1 induces a reduction in PAK1 activity, resulting in upregulation of myosin light chain kinase (MLCK) activity and increased light chain of myosin II (MLC) phosphorylation." (PMID 28430160, 2017). "The use of dominant negative Rac1 and PAK1 mutants reduced macropinocytosis and infection, in contrast to the outcomes achieved with a dominant positive Rac1 mutant, which stimulated the A-MLV infection of mouse embryo fibroblast cells." (PMID 28430160, 2017). "If these effects were inhibited using compounds targeting Na+/H+ exchangers, myosin II, PAK1, and other factors, no infection was observed." (PMID 23593008, 2013). "When expressed in Hap1 cells Emerald-tagged PH-kinase, PH-CPP as well as CRIB-kinase were all successfully recruited by Salmonella after a 10-minute infection, confirming that an exogenous PH domain (and also the CRIB/AID of PAK1 itself) could successfully localise proteins to bacterial entry foci." (PMID 34460869, 2021). "Because EspG has been reported to bind and activate group I PAKs (PAK1, -2, and -3) in vitro and the results above suggest that the interaction between EspG and PAK is of importance in pedestal formation and bacterial attachment, we tested the ability of EspG to activate PAK during infection." (PMID 31431554, 2019). "In addition, VV-GFP uptake was potently blocked by a specific PAK1 inhibitor, suggesting infection does not occur via an alternative mechanism such as membrane fusion." (PMID 26701304, 2015). "The importance of SNX1, VCL and PAK1 for infection of HeLa cells with MHV could not be confirmed (grey)." (PMID 25375324, 2014). "In addition, Cdc42, PAK1, and N-Wasp were required for RSV internalization and infection." (PMID 23593008, 2013). "Infectious internalization and infection were found to be similarly reduced by cytochalasin D (actin polymerization), jasplakinolide (actin depolymerization), EIPA (Na+/H+ exchanger), genistein (tyrosine kinases), PI-103 (PI3K), IPA-3 (PAK-1), and H-7 (serine/threonine kinases)." (PMID 22536154, 2012). "We investigated the Pak1 inhibitor IPA-3, NHE inhibitor amilorid, vacuolar ATPase inhibitor bafilomycin A1, microtubules inhibitor nocodazole, and actin microfilaments inhibitor Latrunculin B, and all these agents failed to suppress GCRV104 infection." (PMID 29793525, 2018). "Interestingly, knocking down macropinocytosis markers PAK-1, CDC42, and ARF6 did not significantly reduce ANDV infection." (PMID 27780263, 2016).
neurodevelopmental disorder (10 papers, 2016 to 2025). A behavioral and cognitive disorder with onset during the developmental period that involves impaired or aberrant development of intellectual, motor, or social functions. "We have also reported the novel c.396C>A (p.Asn132Lys) variant in a 5-year-old girl with neurodevelopmental disorder, adding important data to the expanding literature on PAK1-related conditions." (PMID 41516310, 2025). "To date, three pathogenic variants have been identified within the kinase domain of the PAK1 gene in association with neurodevelopmental disorders." (PMID 41516310, 2025). "In this study, we identify a novel PAK1 variant associated with a terminal 1q microdeletion in a patient with neurodevelopmental disorder." (PMID 36624491, 2023). "However, reported electro‐clinical features of PAK1‐associated neurodevelopmental disorder are distinct from those in PAK3 neurodevelopmental disorder including multi‐focal spike wave and epileptic discharges, and sharp waves in frontal and temporal regions." (PMID 39806575, 2025). "Indeed, PAK1 mutation is relevant to neurodevelopmental disorder showing epileptic symptoms." (PMID 37118736, 2023). "As for the importance of PAK1 in neuronal growth and structure, as well as the previous reported cases, we believe that the de novo PAK1 gene variant in the patient may responsible for the major clinical features of neurodevelopmental disorder." (PMID 36624491, 2023). "Beyond neurodevelopmental disorders, PAK1 inhibition has demonstrated neuroprotective effects in injury models." (PMID 41451871, 2025). "By integrating novel case data with existing literature, this work advances understanding of PAK1-related neurodevelopmental disorders and supports the application of genetic analysis in rare pediatric NDD cases." (PMID 41516310, 2025). "Here, we have summarized the knowledge about changes in the autoregulatory and kinase domain of the PAK1 gene that contribute to the development of neurodevelopmental disorders." (PMID 41516310, 2025).
cardiovascular diseases (6 papers, 2013 to 2025). "For instance, the inhibition of PAK1 precipitates neural impairments, including loss of cognitive function and memory, and also results in cardiovascular disorders." (PMID 40332759, 2025). "Ultimately, future research should pave the way for innovative therapeutic strategies targeting Pak1, offering hope for improved management and treatment of complex metabolic and cardiovascular disorders." (PMID 40065530, 2025). "Considering the important role of Pak1 in cell survival pathways, it holds great promise in the treatment of cardiovascular disease treatment." (PMID 39899001, 2022). "The structure, activation and function of Pak1/2 as well as their protective roles against the occurrence of cardiovascular disease are described in this review." (PMID 39899001, 2022). "Increasing evidences have demonstrated that PAK1 participates in cardiovascular diseases by engaging different signaling pathways." (PMID 34603600, 2021). "These molecular tools should be valuable in further exploring Pak1 function in vivo and serve as drug candidates for novel therapeutics of major cardiovascular diseases." (PMID 24098283, 2013). "Identification of a more specific agonist that turns on Pak1 activities in vivo will not only have application to further define Pak1 function in vivo, but also may serve as a novel therapeutic approach for cardiovascular diseases." (PMID 24098283, 2013). "Given the role of Pak1/2 in the cardiovascular system, strategies targeting Pak1 and Pak2 could be promising avenues for treating cardiovascular disease by maintaining cellular homeostasis, metabolic function, and enhancing cardiomyocyte adaptation and resilience to stress." (PMID 39899001, 2022). "Thus, Pak1 activation holds a great promise in the treatment of cardiovascular disease." (PMID 39899001, 2022). "Accumulating studies have indicated that PAK1 and PAK2 play important roles in transmitting cellular signals and regulating a range of cellular functions, such as cell proliferation, survival, and apoptosis, making them important therapeutic targets in various cardiovascular disorders." (PMID 39766303, 2024).
neurodegenerative disease (6 papers, 2015 to 2025). A disorder of the central nervous system characterized by gradual and progressive loss of neural tissue and neurologic function. "Further studies will optimize NVS‐PAK1‐1 and related PAK1 inhibitors for clinical use, assess long‐term effects, and explore applications to other neurodegenerative diseases." (PMID 41451871, 2025). "Given the role of synaptic dysfunction in AD progression, future studies should investigate the impact of PAK1 inhibition on cognitive outcomes, as well as potential interactions with other AD‐related pathways and other neurodegenerative disease models." (PMID 41451871, 2025). "Although the roles of p21-activated serine/threonine kinase 1 (PAK1) have been reported in some neurodegenerative diseases, details regarding neurodegeneration are still limited." (PMID 27121078, 2016). "PAK1 also regulates the expression of Ataxin-1 that is involved in spinocerebellar ataxia type I, suggesting that PAK1 inhibition may be a therapeutic approach in this orphan neurodegenerative disease." (PMID 36937657, 2023). "In addition, reduced expression levels in the elderly were found for the PAK1 and PAK3 genes, which play a crucial role in neuronal cell fate, polarization, and migration and are implicated in neurodegenerative diseases." (PMID 25977747, 2015).